PTPN14 (protein tyrosine phosphatase non-receptor type 14)
Diseases named in the same sentence as PTPN14 in open-access papers (continued):
Sharing a sentence is not in itself a finding about the gene and the disease.
esophageal cancer (1 paper, 2021). A primary or metastatic malignant neoplasm involving the esophagus. "Here, we studied the role of FAT1 and PTPN14 in the regulation of cell proliferation, adhesion, and invasion during esophageal cancer progression and the possible association with the Hippo pathway." (PMID 34712552, 2021). "FAT1 inhibited the proliferation, adhesion, and invasion of human esophageal cancer cell lines, which might be associated with the upregulation of PTPN14 and the inhibition of Yap1 and Myc." (PMID 34712552, 2021). "Together, these data showed that FAT1 inhibited the cell proliferation, adhesion, and invasion of human esophageal cancer, which might be associated with the upregulation of PTPN14 and inhibition of Yap1 and Myc." (PMID 34712552, 2021). "We also studied FAT1/PTPN14 on proliferation, adhesion, and invasion characteristics of esophageal cancer cell lines by FACS, clone formation assay, and the Transwell method." (PMID 34712552, 2021). "Results showed that FAT1 and PTPN14 were downregulated, while Yap1 was upregulated in esophageal cancer tissues." (PMID 34712552, 2021). "FAT1 promotes the expression of PTPN14 and downregulates the expressions of Yap1 and Myc, to inhibit the proliferation, adhesion, and invasion of human esophageal cancer cell lines." (PMID 34712552, 2021). "Our results showed that FAT1 and PTPN14 are downregulated while Yap1 is upregulated in esophageal cancer tissues." (PMID 34712552, 2021). "This study might provide a theoretical basis on the roles of FAT1 and PTPN14 in the occurrence and development of esophageal cancer." (PMID 34712552, 2021). "However, how FAT1 and PTPN14 regulate the malignant progression and chemotherapy resistance of esophageal cancer is still unclear." (PMID 34712552, 2021). "In this study, we examined the expression levels of Yap1, PTPN14, and FAT1 in human esophageal cancer cell lines and tissues." (PMID 34712552, 2021). "The expression levels of PTPN14 and FAT1 were low in the tissues of esophageal carcinoma, but high in the adjacent tissues of esophageal carcinoma." (PMID 34712552, 2021). "The results suggested that PTPN14 and FAT1 could regulate malignant progression and chemotherapy resistance of esophageal cancer based on the Hippo signaling pathway." (PMID 34712552, 2021).
hepatocellular carcinoma (1 paper, 2022). A malignant tumor that arises from hepatocytes. "The PTPN14 expression in hepatocellular carcinoma (HCC) tissues were evaluated by qRT-PCR, western blot and tissue microarrays." (PMID 35135548, 2022).
Intellectual disability (1 paper, 2019). "Furthermore, what is the role of cancer genes (DDAH1 and PTPN14) shown to have variants with a protective role for intellectual disability." (PMID 30824863, 2019). "This further supports the evidence that some types of cancers and intellectual disability may be mutually exclusive, generating the hypothesis that some cancer related genes like, DDAH1 and PTPN14, may act as protective against some forms of intellectual disability." (PMID 30824863, 2019).
lung adenocarcinoma (1 paper, 2015). A carcinoma that arises from the lung and is characterized by the presence of malignant glandular epithelial cells. "On the other hand, in the primary lung adenocarcinoma samples, although PTPN14 expression levels were lower than in the adjacent unaffected lung, they showed more variation between individuals across the panel (≅ 4 fold)." (PMID 25815003, 2015). "Moreover, in angiogenically active human lung adenocarcinoma tissue, but not in uninvolved quiescent lung, rs10987746-C was correlated with expression of PTPN14 (P = 0.004), another modifier of HHT." (PMID 25815003, 2015).
pancreatic ductal adenocarcinoma (1 paper, 2023). An infiltrating adenocarcinoma that arises from the epithelial cells of the pancreas.
retinoblastoma (1 paper, 2016). A malignant tumor that originates in the nuclear layer of the retina. "Our results are consistent with the model that the targeted degradation of PTPN14 by high-risk E7 could account for some of the retinoblastoma-independent transformation activity of E7 that has been described in the literature for many years." (PMID 27651363, 2016). "We have determined that high-risk E7 proteins target the proteolysis of the cellular protein tyrosine phosphatase PTPN14 and find that this activity is correlated with the retinoblastoma-independent transforming activity of E7." (PMID 27651363, 2016). "Other published data are also consistent with a link between PTPN14 degradation and retinoblastoma-independent transformation." (PMID 27651363, 2016). "PTPN14 degradation requires the N- and C-terminal regions of E7 that are known to be important in retinoblastoma-independent transformation." (PMID 27651363, 2016). "In addition, our results are consistent with the previously identified role of UBR4 in retinoblastoma-independent transformation, since the degradation of PTPN14 in the presence of E7 requires UBR4." (PMID 27651363, 2016). "That retinoblastoma-independent transformation activity mapped to the N and C termini of HPV16 E7, which we now know are required for PTPN14 degradation." (PMID 27651363, 2016). "The ability of E7 to target PTPN14 for degradation maps to the N and C termini of E7 and is independent of RB1 binding by E7, making it consistent with previous suggestions in the literature that there is a retinoblastoma-independent transformation activity of E7." (PMID 27651363, 2016).
Wilms tumor (1 paper, 2018). An embryonal neoplasm characterized by the presence of epithelial, mesenchymal, and blastema components. "Interestingly, Ptpn14 is a negative regulator of Yap and Yap is essential for nephron induction and differentiation, and its subcellular localization is dysregulated in Wilms tumor." (PMID 30166318, 2018).
tumor (49 papers, 2007 to 2026). "PTPN14 is a well-known target of many HPV E7 proteins and is considered a tumor suppressor in part because loss-of-function mutations in PTPN14 are associated with increased cancer risk." (PMID 37036883, 2023). "PTPN14 is defined as a tumor suppressor because inactivating mutations in PTPN14 are associated with increased risk of some cancers." (PMID 37036883, 2023). "Protein tyrosine phosphatase non-receptor type 14 (PTPN14) has been implicated as a tumor suppressor and negative regulator of YAP1." (PMID 35170430, 2022). "As a tyrosine phosphatase, PTPN14 has been shown to form a complex with Yes-associated protein (Yap) and phosphorylate Yap in tumor cells, thereby modulating the Hippo pathway." (PMID 32978373, 2020). "PTPN14 was identified as a possible tumor suppressor through shRNA-mediated loss-of-function screen." (PMID 27240404, 2016). "Our data also implicated that FAT1 might function as the tumor suppression through the promotion of the expression of PTPN14 and inhibition of the expressions of Yap1 and Myc." (PMID 34712552, 2021). "Taken together, we hypothesized that PTPN5 and PTPN14 mainly function in the process of tumor progression, and its correlation with the risk of cancer requires further evaluation and experiments." (PMID 32536826, 2020). "Herein, we examined whether reintroduction of the SQA mutant PTPN14, confirmed to be resistant to E7-associated degradation, could restore the tumor-suppressive function of PTPN14 in HeLa cells." (PMID 31323018, 2019). "E7 proteins from high- and low-risk HPV genotypes bind directly to at least two tumor suppressors, RB1 and PTPN14, and inactivate both." (PMID 41890011, 2026). "PTPN13 and PTPN14, protein tyrosine phosphatases, modulate key signaling pathways involved in tumor progression and metastasis." (PMID 40952239, 2025). "Certain assays of tumor suppression show a mutual requirement for PTPN14 and WWC1 (KIBRA), but potential contributions of WWC2 and WWC3 in the same assays have not been thoroughly tested." (PMID 38496413, 2024). "In our study, the restoration of PTPN14 expression in primary tumor tissue not only inhibited tumor growth, suggesting a potential reduction in the number of tumor cells disseminated into the bloodstream, but also induced anoikis." (PMID 39189475, 2024). "In a mouse model, PTPN14 mRNA‐lipid nanoparticle delivery has reduced tumor growth and metastasis, highlighting its therapeutic potential." (PMID 39189475, 2024). "Conversely, tumors in the control group displayed significant necrotic areas (dashed line annotation), indicating that PTPN14 overexpression substantially suppressed tumor growth." (PMID 39189475, 2024). "The intratumoral injection of LNPs‐encapsulated PTPN14 mRNA successfully inhibited the growth of primary tumors, delayed and reduced the occurrence of distant metastasis, retarded tumor progression, and extended survival." (PMID 39189475, 2024). "The best-characterized mechanism by which PTPN14 acts as a tumor suppressor is by inactivating the YAP1 oncoprotein, a potent driver of cell stemness and self-renewal (29, 31, –, 34, 36)." (PMID 39248565, 2024). "The best-characterized mechanism by which PTPN14 acts as a tumor suppressor is by inactivating the YAP1 oncoprotein, a potent driver of cell stemness and self-renewal." (PMID 38496413, 2024). "We and others have determined that many HPV E7 proteins also target a second tumor suppressor, Protein Tyrosine Phosphatase Non-receptor Type 14 (PTPN14)." (PMID 38496413, 2024). "Achieving cancer cell‐specific delivery will enable PTPN14 mRNA to target tumor cells effectively, positioning it as a powerful anticancer drug." (PMID 39189475, 2024). "Corresponding to this result, tumor growth in the PTPN14 mRNA‐LNPs treatment group was significantly slower than that in the two control groups." (PMID 39189475, 2024).
tumor (continued). "PTPN14 is mutated or its expression is reduced in several cancer types, and data from human cancer studies and cell-based assays provide evidence for the tumor suppressive activity of PTPN14 (23, –, 34)." (PMID 39248565, 2024). "In contrast, the boundary between the tumor and normal tissues was well‐defined in the PTPN14 mRNA‐LNPs treatment group, indicating that therapy with PTPN14 mRNA‐LNPs reduced tumor progression." (PMID 39189475, 2024). "Local delivery of in vitro transcribed PTPN14 mRNA encapsulated by lipid nanoparticles in a TNBC mouse model has effectively inhibited tumor growth and metastasis, prolonging survival." (PMID 39189475, 2024). "Since PTPN14 is a well-known tumor suppressor, degradation of PTPN14 helps to promote the transformation and immortalization of HPV-infected cells." (PMID 38416831, 2024). "For instance, fusions of oncogenic proteins TAZ, YAP1, and HIPK2 preserve their tumor-promoting function, while fusions of tumor suppressors, such as NF2, LATS1, FAT1, PTPN14, DCHS2, TAOK1, and TAOK3, results in loss of their function." (PMID 38499647, 2024). "At different time points postinjection, the measurement data of tumor size showed that the tumor growth rate in the control group was faster than that in the PTPN14‐OE group." (PMID 39189475, 2024). "Further correlation analysis indicated that PTPN14 was relevant with the T stage and cTNM (clinical tumor node metastasis classification) stage." (PMID 36898991, 2023). "Low levels of PTPN14 expression, a downstream regulatory protein of stathmin, endows progeny tumor cells generated by PGCCs with the ability to invade and metastasize." (PMID 37476197, 2023). "The tumor volume was significantly higher in HepG2 cells with PTPN14 knockdown and was significantly lower in SK-Hep1 cells with PTPN14 overexpression." (PMID 35135548, 2022). "Silencing PTPN14 significantly enhanced proliferation, migration, invasion of HepG2 cells in vitro and tumor growth and metastasis in vivo, whereas overexpression of PTPN14 significantly inhibited these abilities in SK-Hep1 cells." (PMID 35135548, 2022). "To confirm these results in vivo, we subcutaneously injected HepG2 cells with stable knockdown of PTPN14 as well as SK-Hep1 cells with stable overexpression of PTPN14 into nude mice and measured tumor growth over 5 weeks." (PMID 35135548, 2022). "This is consistent with our data indicating that PTPN14 acts as a tumor suppressor in KRASG12V-transformed cells." (PMID 34815476, 2021). "This is the first report linking the tumor suppressor function of PTPN14 to regulation of Y14-CAV1 phosphorylation." (PMID 32152405, 2020). "Among the eight upregulated genes observed for cell adhesion, migration, and invasion, we detected three genes positively regulating cell adhesion and affecting tumor dissemination (Ptpn14, Myl12b, and Emp2)." (PMID 29108266, 2017). "PTEN and PTPN14 have been shown to play crucial roles in cell proliferation and tumor growth by regulating mTOR and Hippo signaling pathways." (PMID 25803229, 2015). "The immunoreactivity of the BNIP3L and PTPN14 staining was strong in the primary tumour (score 3), whereas weak staining was observed in the liver metastases (score 1)." (PMID 17940512, 2007). "PTPN14, an upstream regulator of the Hippo pathway, functions as a tumor suppressor." (PMID 41256331, 2025).
tumor (continued). "Even without systemic administration of PTPN14 mRNA, mice treated with PTPN14 mRNA, compared to the control group, showed alleviated tumor metastasis, suppressed cancer progression, and achieved complete remission in one case within the PTPN14 mRNA LNPs treatment group." (PMID 39189475, 2024). "PTPN14 encodes the protein tyrosine phosphatase non-receptor type 14, which is a tumor-suppressor gene, and loss-of-function and deleterious missense mutations in this gene have been linked to BCC tumorigenesis." (PMID 38182794, 2024). "We also examined the alterations in tumor growth following PTPN14 overexpression." (PMID 39189475, 2024). "A likely tumor suppressive activity of PTPN14 is its inhibition of YAP function." (PMID 37036883, 2023). "A tumor suppressive activity of PTPN14 is to inhibit YAP activity." (PMID 37036883, 2023). "However, PTPN14 exerts the role of a tumor suppressor gene by dephosphorylating the specific substrate protein." (PMID 36898991, 2023). "In addition, circ_AKT3, PTPN14 and P-gp levels were reduced and miR-206 abundance was increased in tumor samples from sh-circ_AKT3 group in comparison to sh-NC group." (PMID 35233464, 2022). "In contrast, PTPN13 and PTPN14 function as tumor suppressors in prostate cancer." (PMID 35957898, 2022). "Similarly, tumor weight was significantly higher in HepG2 cells with PTPN14 knockdown and significantly lower in SK-Hep1 cells with PTPN14 overexpression." (PMID 35135548, 2022). "PTPN14 is a tumor suppressor that we found restricts cell growth by promoting differentiation." (PMID 36346242, 2022). "Therefore, our data indicate that PTPN14 likely acts as a tumor suppressor through a Yap/Hippo-independent mechanism involving apical-basal polarity in this model of KRASG12V malignant transformation." (PMID 34815476, 2021). "Moreover, we revealed a role for PTPN14 as a tumour suppressor that regulates cell polarity and epithelial organization in KRASG12V-transformed epithelial cells." (PMID 34815476, 2021). "Therefore, our study indicates that PTPN14 likely has additional Yap-independent tumor suppressor functions by regulating cell polarity." (PMID 34815476, 2021). "Thus, while PTPN14 clearly functions as a tumor and metastasis suppressor, little information is available about relevant PTPN14 targets." (PMID 32152405, 2020). "Taken together, removal of tumor-suppressive PTPN14 by E7-mediated degradation should be responsible for the enhanced cell proliferation, migration, and invasion of HPV18-infected cells, which could be inhibited by blocking their complex formation." (PMID 31323018, 2019). "Recent studies revealed Hippo signaling as the major target of PTPN14 for tumor suppression, which mainly relies on the intermolecular interaction between the PPxY domain of PTPN14 and YAP or large tumor suppressor 1 (LATS1), key Hippo signaling pathway components." (PMID 31323018, 2019). "Moreover, PTPN14 was reported to be involved in the suppression of tumor cell metastasis by restricting intracellular protein trafficking." (PMID 31323018, 2019). "In addition to the cancer cell signaling work that has been done, genetic profiling is also supporting PTPN14’s emerging role as a tumor suppressor." (PMID 27240404, 2016). "Enhanced understanding of process such as tumor cell proliferation and apoptosis that are regulated by miR-21, and the identification of critical targets for individual miRNAs such as PTPN14 and PTEN, provides novel insights into the mechanisms of carcinogenesis and progression in ICC." (PMID 25803229, 2015). "PTPN14 is a member of the protein tyrosine phosphatase family, which is increased in many tumours, indicating that a complex dysregulation in the balance of tyrosine phosphorylation could be responsible for major alterations in various cellular processes." (PMID 17940512, 2007). "Furthermore, mRNA therapy aimed at restoring PTPN14 inhibits both tumor growth and metastasis." (PMID 39189475, 2024).